DDR1 (discoidin domain receptor tyrosine kinase 1)
Diseases named in the same sentence as DDR1 in open-access papers (continued):
Sharing a sentence is not in itself a finding about the gene and the disease.
hepatocellular carcinoma (24 papers, 2010 to 2025). A malignant tumor that arises from hepatocytes. "Previous work has reported that in leukemia and in hepatoma cells decreased miR-199a-5p was associated with DDR1 upregulation." (PMID 26655502, 2016). "It has been shown that over-expression of DDR1 increased the migration and invasion of hepatoma cells in vitro, which implicated a role of DDR1 in tumor progression and metastatic dissemination." (PMID 26297342, 2015). "Over-expression of DDR1 has been shown to increase the migration and invasion of hepatoma cells in vitro, implicating a causal role of DDR1 in promoting tumor progression." (PMID 20799954, 2010). "IHC staining and scoring showed that the levels of DDR1 were elevated in TNM stage II-IV hepatocellular carcinoma tissues in comparison with TNM stage I tissues." (PMID 35140331, 2022). "In this study, we have demonstrated that EFA6B promotes the migration and invasion of hepatocellular carcinoma cells, and is required for DDR1-mediated ARF6 activation." (PMID 35140331, 2022). "Detailed Cell function and mice model studies demonstrated that DDR1 played a crucial role in the metastasis of hepatocellular carcinoma." (PMID 35140331, 2022). "In cancers such as hepatocellular carcinoma and acute myeloid leukemia, DDR1 expression has been shown to be anti-correlated with miR-199a16." (PMID 34837026, 2021). "In hepatocellular carcinoma, DDR1-induced linear invadosome formation is enhanced in the presence of TGFβ1." (PMID 33917302, 2021). "It was recently shown that DDR1 is activated in the presence of C1q, with phosphorylation at Tyr513 of DDR1 in hepatocellular carcinoma." (PMID 33917302, 2021). "In hepatocellular carcinoma cells, a cross-talk between DDR1 and STAT3 enhances tumor progression by promoting proliferation, migration and invasion in vitro, and tumorigenesis in vivo." (PMID 33917302, 2021). "DDR1 promotes adhesion to collagen of a variety of malignant cells, including pituitary adenoma, glioma, and hepatoma cells." (PMID 32090682, 2020). "Specifically, miR-199a-5p has been reported to target DDR1 in hepatocellular carcinoma, acute myeloid leukemia, colorectal cancer and cutaneous squamous cell carcinoma." (PMID 31253192, 2019). "Elevated DDR1 expression has also been reported in: (i) 52.2 % of hepatocellular carcinoma samples; (ii) 61.0 % of non-small cell lung cancer; and (iii) 63 % of serous ovarian cancer tissues." (PMID 26297342, 2015). "MiR-199a-5p, which is partially complementary to the 3' UTR of DDR1 mRNA, induced significant degradation of DDR1 mRNA in hepatoma cells in our study." (PMID 20799954, 2010). "Although the involvement of DDR1 in inhibiting the Hippo pathway to enhance hepatocellular carcinoma cell stemness has been documented, its role in regulating the Hippo pathway in GC remains unclear, despite various proposed DDR1 downstream pathways." (PMID 40456688, 2025). "Indeed, high expression of DDR1 has also been identified in 52.2% of hepatocellular carcinoma samples, 61.0% of non-small cell lung cancer, and 69% of serous ovarian cancer tissues." (PMID 35205677, 2022). "In addition to COL1A1 and DDR1 knockdown, ZEB1 suppression significantly decreased SNU449 cell invasiveness, implying involvement of the COL1A1/DDR1/ZEB1 axis in hepatoma cell invasiveness." (PMID 34772924, 2021). "DDR1 induces EMT in hepatocellular carcinoma by regulating STAT3 in vitro and in vivo." (PMID 33917302, 2021). "Our results reveal a relationship between C1q and DDR1 and suggest C1q-induced DDR1 activation signaling may be involved in the progression of hepatocellular carcinoma." (PMID 29559654, 2018). "Interestingly, previous findings suggested that miRNA-199a-5p directly regulated the expression of DDR1 in hepatocellular carcinoma." (PMID 28743276, 2017). "In addition, SNU-182 hepatoma cells exhibited increased levels of expression of both miR-199a-5p and DDR1 mRNA." (PMID 20799954, 2010).
hepatocellular carcinoma (continued). "Besides, increased DDR1 is known to be associated with the progression and poor prognosis of non-small cell lung carcinoma, hepatocellular carcinoma, bladder cancer, and oral squamous cell carcinoma, indicating an important role of DDR1 in in tumor progression." (PMID 39567474, 2024). "However, the effect of miR-199a-5p on DDR1 varies among individuals and hepatoma cell lines." (PMID 20799954, 2010). "Our results reveal that the DDR1/PSD4/ARF6 signaling axis acts as an important inducer in the regulation of the migration, invasion and lung metastasis of hepatocellular carcinoma cells by collagen induced DDR1 signaling." (PMID 35140331, 2022). "Interestingly, there are some shreds of evidence about how the cross-taking of DDR1 and STAT3 contributes to the development of hepatocellular carcinoma." (PMID 37271822, 2023). "In hepatocellular carcinoma, DDR1 activates STAT3 which, in turn, increases DDR1 mRNA expression." (PMID 33917302, 2021). "As previously reported in human hepatoma Huh7 cells, tumor DDR1 appeared constitutively phosphorylated in the absence of exogenous collagen." (PMID 32090682, 2020). "For instance, transfection of miR-199a-5p in hepatoma cells significantly down-regulated DDR1 protein but did not induce changes in DDR1 mRNA expression." (PMID 26655502, 2016). "Ddr1 has not been studied extensively in the liver, but overexpression of Ddr1 has been detected in diseased human liver and in early recurrence of hepatocellular carcinoma." (PMID 24391948, 2013). "Similarly, in two out of five hepatoma cell lines, HepG2 and SNU-182, DDR1 expression was significantly (p < 0.001) upregulated compared to primary human hepatocytes." (PMID 20799954, 2010). "In hepatocellular carcinoma (HCC), type I collagen promotes cancer cell stemness and metastasis through the CD44/DDR1/YAP axis and the PSD4/ARF6 signaling pathway, respectively." (PMID 40563472, 2025). "Research indicated that the cross-talk between DDR1 and signal transducer and activator of transcription 3 (STAT3) promoted the progression of hepatocellular carcinoma (HCC) via epithelial–mesenchymal transition (EMT) and glutamine metabolism." (PMID 35935941, 2022). "However, only transfection of DDR1-siRNA (p = 0.002) but not of miR-199a-5p precursors (p = 0.820) significantly decreased invasion of another hepatoma cell line, namely SNU-182." (PMID 20799954, 2010).
colorectal cancer (20 papers, 2016 to 2025). A primary or metastatic malignant neoplasm that affects the colon or rectum. "The molecular profile associated with DDR1 high expression could be integrated into the CMS4 molecular subtype of colorectal cancer." (PMID 35205677, 2022). "Overexpression of DDR1 in LoVo human colorectal cancer cells enhances their resistance to 5-Fluorouracil (5-FU)." (PMID 40563472, 2025). "In osteosarcoma and colorectal cancer cell lines, activated DDR1 upregulates Bcl-xl, an anti-apoptotic protein that aids cancer cell survival under therapeutic stress, such as γ-irradiation, actinomycin D, adriamycin, or mitomycin C." (PMID 40563472, 2025). "For instance, discoidin domain receptor 1 (DDR1) is a passive immune modulator of colorectal cancer." (PMID 38577615, 2024). "Recent studies on in vivo models of breast and colorectal cancers have shown that DDR1 affects immune cell composition and infiltration into the TME." (PMID 38136314, 2023). "NSD2 circular RNA aggravates liver metastasis of colorectal cancer by regulating miR-199b-5p/DDR1/JAG1 axis." (PMID 37709489, 2023). "In a previous immunohistochemical study, high DDR1 immunoreactivity score was correlated with a shorter overall survival in a cohort of 100 patients with colorectal cancer." (PMID 35205677, 2022). "To fill this gap, we investigated the potential role of DDR1 in tumor cell invasion by using several colorectal cancer cell lines that differentially express DDR1." (PMID 35205677, 2022). "Preliminary results indicated that the expression of DDR1 was significantly related to the prognosis of patients with various cancer types, including blood, brain, ovarian, lung, prostate, breast and colorectal cancers." (PMID 35935941, 2022). "In colorectal cancer, downregulation of miR-199a-5p increases DDR1 expression, resulting in increased expression of mesenchymal markers." (PMID 33917302, 2021). "Modulation and regulation of MMP2 and/or MMP9 activity by DDR1 have also been demonstrated in pituitary adenoma, colorectal cancer, and renal cancer (MMP2)." (PMID 33917302, 2021). "The effect of DDR1 inhibition on cystogenesis was validated in CaCO-2 cells, a well-differentiated human colorectal carcinoma cell line." (PMID 30760555, 2019). "Meanwhile, others reported that DDR1 upregulation promoted tumor progression by reducing E-cadherin expression in lung and colorectal cancers." (PMID 28143619, 2017). "In colorectal cancer cells, miR-199a-5p was found to interact with discoidin domain receptor 1 (DDR1), a receptor tyrosine kinase." (PMID 26717044, 2016). "Furthermore, in colorectal cancer, DDR1 activates breakpoint cluster region (BCR) to sustain β-catenin transcriptional activity, a key regulator of cancer cell invasion." (PMID 40563472, 2025). "Recently, multiple studies on breast and colorectal cancers have shown initial evidence that DDR1 could affect T-cell infiltration into the TME, mostly due to its interaction with collagen." (PMID 38136314, 2023). "However, initial evidence from recent studies on breast and colorectal cancers have shown that DDR1 could play a role in T-cell infiltration." (PMID 38136314, 2023). "Thus, the overexpression of DDR1 in these malignant diseases, particularly in colorectal cancer, supports the hypothesis that DDR1 upregulation is widespread in cancer and can play an important role in tumorigenesis and/or tumor invasion and metastasis." (PMID 35205677, 2022). "In colorectal cancer, low-density lipoprotein receptor-related protein 1 (LRP-1) regulates DDR1 expression via endocytosis, promoting cell cycle progression into the S-phase and enhancing tumor proliferation." (PMID 40563472, 2025).
colorectal cancer (continued). "DDR1 activates the PI3K/AKT/PKM2 signaling pathway, facilitating glucose reprogramming in colorectal cancer cells, thereby supporting intracellular homeostasis and cell proliferation." (PMID 40563472, 2025). "In colorectal cancer, NSD2 (Nuclear Receptor Binding SET Domain Protein 2) circular RNA inhibits miR-199b-5p expression, which leads to an upregulation of DDR1 expression and promotes migration and invasion in vitro and in vivo." (PMID 33917302, 2021). "Specifically, DDR1-high tumors showed marked depletion of CD8+ cytotoxic T cells and enrichment of immunosuppressive Tregs, consistent with observations in other tumor types such as TNBC and microsatellite-stable colorectal cancer." (PMID 40869052, 2025).
colon carcinoma (19 papers, 2016 to 2025). "We then demonstrated that LRP-1 and DDR1 are tightly associated in the same biomolecular complexes at the plasma membrane of colon carcinoma to constitute a new endocytosis complex." (PMID 32582700, 2020). "The findings of this study have highlighted the first ever molecular association between LRP-1 and DDR1 in colon carcinoma." (PMID 32582700, 2020). "This study aimed to evaluate the clinical and prognostic impact of Discoidin Domain Receptor 1 (DDR1) expression in colon cancers and its association with a particular molecular and/or morphological profile and to evaluate its potential role as a prognosis biomarker." (PMID 35205677, 2022). "Kaplan–Meier survival analysis was conducted to evaluate the prognostic value of DDR1 expression across ovarian, breast, lung, gastric, pancreatic, and colon cancer cohorts." (PMID 40869052, 2025). "DDR1 promoted the intrahepatic metastasis of colon cancer by interacting with liver stromal cells to regulate liver stromal remodeling." (PMID 37031216, 2023). "For instance, a previous study concluded that colon cancer cells with DDR1 overexpression have the ability to survive more due to the activation of Notch1 which stimulates the expression of pro-survival genes Hes1 and Hey2." (PMID 37271822, 2023). "BCR was identified as a DDR1 target in colon carcinoma cells using quantitative phosphoproteomics to identify proteins phosphorylated in response to DDR1 activation." (PMID 34941574, 2022). "Our immunohistochemical study indicated that DDR1 is highly expressed in colon cancer compared to normal colonic mucosa and its expression is associated with shorter event-free survival." (PMID 35205677, 2022). "This overexpression of DDR1 is found in a large majority of colon cancers, suggesting a role of DDR1 in colorectal carcinogenesis." (PMID 35205677, 2022). "A recent study showed DDR1 as a therapeutic target in colon cancer, activating BCR signaling downstream." (PMID 35664781, 2022). "The relationship between DDR1 expression and disease aggressiveness was investigated in a cohort of 292 colon cancer patients." (PMID 35205677, 2022). "The LRP-1 mediated endocytosis of DDR1 supports colon carcinoma cell proliferation by promoting the entry of cell cycle to the S phase and decreasing apoptosis." (PMID 32582700, 2020). "Reverse immunoprecipitation experiments with anti-DDR1 were also performed using the same cell lysates and confirmed that LRP-1 and DDR1 were detected in the same molecular complexes in colon carcinomas." (PMID 32582700, 2020). "In a coherent way, overexpression of DDR1 in HT-29 cells favors cell cycle arrest and apoptosis of colon carcinoma in 3D environment." (PMID 32582700, 2020). "In colon carcinoma cells, DDR1 regulates the cleavage of Notch 1 by a γ-secretase and the subsequent release and translocation of its intracellular domain to the nucleus to stimulate pro-survival genes." (PMID 32582700, 2020). "We found that LRP-1 established tight molecular connections with DDR1 at the plasma membrane in colon cancer cells." (PMID 32582700, 2020). "T4H11‐DM4 demonstrated potent antitumor efficacy both in vitro and in vivo with an acceptable safety profile, suggesting anti‐DDR1 ADC is a promising strategy for colon carcinoma therapy." (PMID 31116512, 2019). "The DDR1 cell‐surface localization and swift endocytosis characteristics make it a targetable antigen for the ADC and compelled us to assess the potential DDR1‐targeted ADC colon carcinoma therapy." (PMID 31116512, 2019). "Here, we employed an antibody‐based strategy with a novel anti‐DDR1 antibody‐drug conjugate (ADC) for colon carcinoma treatment." (PMID 31116512, 2019). "Other colon cancer cell lines with varying surface expression levels of DDR1 exhibited IC50 ranging from 60.6 to 135.3 nm." (PMID 31116512, 2019).
colon carcinoma (continued). "We identified that DDR1 has suitable characteristics for development as an ADC target for a novel colon cancer treatment approach, including elevated expression, cell‐surface localization and swift endocytosis." (PMID 31116512, 2019). "In vivo, the antitumor efficacy of T4H11‐DM4 was evaluated in three colon cancer cell lines expressing different levels of DDR1." (PMID 31116512, 2019). "Taking together, these results confirmed the potential of DDR1 as a target for the treatment of colon cancer." (PMID 31116512, 2019). "Immunohistochemical analysis of a tissue microarray containing 100 colon cancer specimens revealed that DDR1 was highly expressed in 81% of tumor tissues." (PMID 31116512, 2019). "Our data demonstrated that a novel anti‐DDR1 ADC potently and selectively killed DDR1‐positive colon cancer cells in vitro and eliminated the DDR1‐positive colon carcinoma in xenograft models." (PMID 31116512, 2019). "First, DDR1 expression was examined in colon cancer cell lines resistant to oxaliplatin named SW480‐OR and HCT116‐OR by FCM." (PMID 31116512, 2019). "Hu and co-workers showed that overexpression of DDR1 induces invasion in colon carcinoma through the up-regulation of MMP-2." (PMID 27014069, 2016). "Consistently, studies in human HCT116 colon carcinoma cells showed that DDR1, in response to collagen-induced activation, promotes cell survival in a Notch signaling manner." (PMID 27014069, 2016). "In colon carcinoma, the role of DDR1 remains incompletely elucidated." (PMID 35205677, 2022). "DDR1 was highly expressed in a large majority (82.2%) of colon cancers." (PMID 35205677, 2022). "In summary, DDR1 is highly expressed in colon cancer compared to normal colonic mucosa." (PMID 35205677, 2022). "This negative correlation between Zeb1 and DDR1 is significantly associated in a female-specific manner in breast, ovarian, and liver cancers but not in lung or colon cancers." (PMID 33917302, 2021). "DDR1 is expressed in colon carcinoma and promote metastasis in invasive colon carcinoma." (PMID 32426274, 2020). "Here, we addressed whether it could exist functional interplays between LRP-1 and DDR1 to control colon carcinoma cell behavior in three-dimensional (3D) collagen matrices." (PMID 32582700, 2020). "In this study, we identified a new molecular way that controls the cell-surface expression of DDR1 and consequently the colon carcinoma cell proliferation and apoptosis and highlighted an additional mechanism by which LRP-1 carries out its sensor activity of the tumor microenvironment." (PMID 32582700, 2020). "C26 colon carcinoma secretomes increased DDR1 phosphorylation in HSCs and KCs by collagen I. Inhibition of kinase activity by DDR1-IN-1 or mRNA silencing of DDR1 reduced HSCs secretion of MMP2/9 and chemoattractant and proliferative factors for LSECs and C26 cells." (PMID 33110221, 2020). "Considering that LRP-1 induced HT29 cell proliferation in 3D collagen matrices and drives endocytosis of DDR1, we assume that the cell-surface expression level of DDR1 may constitute a key parameter to control growth and survival of colon cancer cells." (PMID 32582700, 2020). "Indeed, we showed that the endocytic receptor LRP-1 established tight molecular connections with DDR1 at the plasma membrane of colon cancer cells." (PMID 32582700, 2020). "Furthermore, IHC studies showed frequent high expression DDR1 among colon cancer patients with a concomitant restricted normal tissue expression profile." (PMID 31116512, 2019). "Furthermore, OS was significantly shorter in the high DDR1 expression group than the low DDR1 expression group of patients with colon cancer (P = 0.0084)." (PMID 31116512, 2019). "We next detected DDR1 expression in human colon cancer cell lines by FCM." (PMID 31116512, 2019). "We turned to chemotherapy‐resistant colon cancer cell lines to determine whether DDR1‐ADC demonstrate effective activity." (PMID 31116512, 2019).